CENPL (centromere protein L)
Description:
Component of the CENPA-CAD (nucleosome distal) complex, a complex recruited to centromeres which is involved in assembly of kinetochore proteins, mitotic progression and chromosome segregation. May be involved in incorporation of newly synthesized CENPA into centromeres via its interaction with the CENPA-NAC complex.
Synonyms: CENP-L; C1orf155; dJ383J4.3; FLJ31044
Tractability: PROTAC: ubiquitination databases record sites on it.
Gene: Protein-coding gene on chromosome 1 (173,799,550 to 173,824,883, reverse strand). Ensembl gene ENSG00000120334.
Subcellular location: Nucleus; Chromosome, centromere
Pathways (Reactome):
Cell Cycle: Amplification of signal from unattached kinetochores via a MAD2 inhibitory signal; Deposition of new CENPA-containing nucleosomes at the centromere; EML4 and NUDC in mitotic spindle formation; Mitotic Prometaphase; Resolution of Sister Chromatid Cohesion; Separation of Sister Chromatids
Signal Transduction: RHO GTPases Activate Formins
Gene Ontology:
Molecular function: protein binding
Biological process: chromosome segregation
Cellular component: inner kinetochore; cytosol; nucleoplasm; nucleus; chromosome, centromeric region
Genetic constraint (gnomAD): Loss-of-function variants: 12 observed, 26.32 expected, observed/expected ratio (o/e) 0.46, 90% interval 0.29 to 0.74. The upper end of that interval is the gene's LOEUF score, 0.74, which puts it in group 3 of 6, group 1 being the genes least tolerant of losing a copy. Missense variants: 280 observed, 333.71 expected, observed/expected ratio (o/e) 0.84, 90% interval 0.76 to 0.93. Synonymous variants: 111 observed, 116.41 expected, observed/expected ratio (o/e) 0.95, 90% interval 0.82 to 1.12.
Homologues: Orthologues: chimpanzee CENPL (99% identical), macaque CENPL (96% identical), pig CENPL (93% identical), guinea pig CENPL (90% identical), rabbit CENPL (89% identical), dog CENPL (87% identical), mouse Cenpl (85% identical), rat Cenpl (85% identical), tropical clawed frog cenpl (53% identical), zebrafish cenpl (39% identical).